OGT (O-linked N-acetylglucosamine (GlcNAc) transferase)
Diseases named in the same sentence as OGT in open-access papers (continued):
Sharing a sentence is not in itself a finding about the gene and the disease.
autoimmune disease (3 papers, 2017 to 2022). A disorder resulting from loss of function or tissue destruction of an organ or multiple organs, arising from humoral or cellular immune responses of the individual to their own tissue constituents. "We believe that further characterisation of the role of OGT and O-GlcNAc modification in autoimmunity may yield new therapeutic targets for autoimmune diseases with inflammatory components." (PMID 35203353, 2022). "When we generated Treg cell-specific OGT knockout (KO) using the Foxp3YFP-Cre mice with YFP-Cre knocked into the endogenous Foxp3 locus, hemizygous male KO mice developed scurfy phenotypes and died of autoimmune disease by the age of 4 weeks, thus preventing us to study their whole-body metabolism." (PMID 35874700, 2022).
Cerebral ischemia (3 papers, 2015 to 2025). Restriction of arterial blood supply to the brain associated with insufficient oxygenation to support the metabolic requirements of the tissue. "Recent studies have highlighted the protective effect of APS on cerebral ischemia–reperfusion injury through enhanced OGT‐induced O‐GlcNAcylation." (PMID 41372976, 2025). "To verify the role of O-GlcNAcylation in cerebral ischemia-reperfusion injury, we studied the MCAO-induced brain damage and motor deficits in mice after the neuronal OGT was selectively knocked out." (PMID 28878265, 2017).
clear cell renal cell carcinoma (3 papers, 2024 to 2025). "O-GlcNAc transferase (OGT) is upregulated in clear cell renal cell carcinoma, and promotes proliferation, colony formation and invasion of tumor cells." (PMID 40050614, 2025). "OGT was found to increase HIF-2α protein levels in clear cell renal cell carcinoma by inhibiting ubiquitin-proteasome-mediated degradation." (PMID 39285476, 2024). "In addition, higher expression of OGT, FOXC1, ASNS, GPT2, CBS, or FTH1 was also associated with poorer outcomes in clinical cases with renal clear cell carcinoma or glioma." (PMID 40416363, 2025). "Moreover, the OGT/HIF-2α axis modulates the sensitivity of clear cell renal cell carcinoma to ferroptosis." (PMID 39285476, 2024).
cognitive deficit (3 papers, 2022 to 2024). "Decreased expression of OGT and lowered O-GlcNAc levels have been found to be linked to certain cognitive disorders, while elevated expression of OGT and increased O-GlcNAc levels are often associated with metabolic diseases including cancer." (PMID 37838167, 2023). "We provide evidence that the Drosophila equivalent of the A319T mutation in the TPR domain of OGT causes a cognitive deficit and support a causal role of A319T in OGT-CDG." (PMID 35500025, 2022). "Moreover, our genetic approach points to a key role of O-GlcNAc transferase activity in ID-associated cognitive deficits and identifies blocking O-GlcNAc hydrolysis as a treatment strategy that can ameliorate cognitive deficits in OGT-CDG patients." (PMID 35500025, 2022). "The data support a causal role of A319T in OGT-CDG and demonstrate that Drosophila habituation can be used to analyze the contribution of OGT mutations to cognitive deficits." (PMID 35500025, 2022). "Therefore, the demonstration here that GlcN or OGT overexpression suppresses neuroinflammation holds promise for mitigating the cognitive impairment and AD pathology induced by CSD." (PMID 39044290, 2024).
lupus (3 papers, 2014 to 2023). "In terms of autoimmune or inflammatory diseases, increased expression of X-linked genes, including OGT, is linked with lupus in women." (PMID 32349769, 2020). "In systemic lupus erythematosus, T cells in female patients display elevated levels of OGT expression and OGT demethylation." (PMID 37675125, 2023). "The authors reported that lupus flares correlated with a hypomethylated OGT promoter and an increase in OGT levels." (PMID 25136351, 2014). "These authors have posited that the increased OGT expression and O-GlcNAcylation level, may trigger or worsen lupus development." (PMID 25136351, 2014).
lymph node metastasis (3 papers, 2015 to 2019). "The presence of higher levels of OGT transcripts in SCLC was associated with a larger tumor size, more frequent incidence of cervical lymph node metastases and higher histological grade." (PMID 25315705, 2015). "Patients with a higher pStage (stages III and IV), more lymph node metastasis (>5) and a higher N stage (N 2 and N 3) had significantly higher OGT expression than those with a low pStage (stages I and II), less lymph node metastasis (≤5) and a lower N stage (N 0 and N 1)." (PMID 31410220, 2019). "Similarly, the level of OGT in GC was significantly associated with Lauren type, pStage, lymph node metastasis and the number of positive lymph nodes but was not related to gender, distant metastasis or depth of invasion." (PMID 31410220, 2019).
myeloma (3 papers, 2021 to 2025). "In contrast, resistance of RPMI8226 cells to bortezomib, a drug used commonly to treat myeloma, was associated with increased O-GlcNAcylated protein levels and reversed by inhibiting OGT." (PMID 34868034, 2021). "Moreover, analysis of the GEO dataset GSE24080 suggests high OGT mRNA expression in primary myeloma cells is associated with an adverse outcome." (PMID 34868034, 2021). "Public databases suggest O-GlcNAcylation is actually reduced in myeloma as OGA was significantly higher in 133 primary myeloma samples compared to normal plasma cells from 5 normal donors with similar OGT expression." (PMID 34868034, 2021). "In this study, we first identified O-GlcNAcylation transferase (OGT) as a key hub gene for MM pathogenesis via three machine learning models based on the RNA microarray data of purified myeloma plasma cell samples from five independent MM cohorts with 957 MM patients." (PMID 39984622, 2025). "In this study we performed machine learning in the RNA microarray data of purified myeloma plasma cell samples from five independent MM cohorts with 957 MM patients, and identified O-GlcNAcylation transferase (OGT) and cell division cycle 27 (CDC27) as the key prognostic genes for MM." (PMID 39984622, 2025). "OGT levels are high in hematological cancer cell-lines and highest in myeloma models." (PMID 34868034, 2021).
pancreatitis (3 papers, 2021 to 2023). Inflammation of the pancreas. "In this study, a mouse model with pancreatic OGT loss was generated and subjected to cerulein, a common pancreatitis inducer." (PMID 35336721, 2022). "OGT has been reported to regulate NF-κB and is required for NF-κB activation and inflammation in different diseases, such as pancreatitis and lung metastasis." (PMID 37835439, 2023). "Our study identified an increase in Ccl2 when pancreatitis was induced in mice with reduced pancreatic OGT; this result is consistent with this previous work in the context of vascular injury." (PMID 35336721, 2022). "Our study reveals the effect of reducing pancreatic OGT levels on the severity of pancreatitis, warranting further investigation on the role of OGT in the pathology of AP." (PMID 35336721, 2022). "This is consistent with previous in vitro work that demonstrated that decreased OGT reduces the severity of pancreatitis, but a significant effect on the genes involved in the NFκB pathway was not identified in the current model." (PMID 35336721, 2022). "In conclusion, this study reveals the functional importance of OGT in the induction of cerulein-induced pancreatitis in vivo using female OGTPanc+/− mice." (PMID 35336721, 2022).
type 2 diabetes (3 papers, 2022). "Global O-GlcNAcylation levels were found augmented in type 2 diabetic patients, and OGT deletion specifically in skeletal muscle in mice improved insulin sensitivity and increased GLUT4 protein levels in gastrocnemius muscle of the KO mice in comparison to control mice." (PMID 35527999, 2022). "In leucocytes from patients with type 2 diabetes, the TXNIP mRNA level was significantly correlated with OGA, but not with OGT mRNA." (PMID 35887161, 2022).
amyotrophic lateral sclerosis (2 papers, 2025 to 2026). Amyotrophic lateral sclerosis (ALS) is a neurodegenerative disease characterized by progressive muscular paralysis reflecting degeneration of motor neurons in the primary motor cortex, corticospinal tracts, brainstem and spinal cord. "In the brain, reduced O-GlcNAc levels, which can arise from insufficient OGT activity, have been increasingly linked to aging-related neurodegenerative diseases such as Alzheimer's, Parkinson's, and amyotrophic lateral sclerosis." (PMID 41629214, 2026).
Arrhythmia (2 papers, 2013 to 2022). Any cardiac rhythm other than the normal sinus rhythm. "We found that reducing activity of either OGT or GFAT specifically in the adult Drosophila heart led to improved heart function as demonstrated by reduced incidence of arrhythmias in the presence of an HSD." (PMID 23326243, 2013).
atherosclerosis (2 papers, 2023 to 2025). A disease characterized by the build-up of fatty material and calcium deposition in the arterial wall resulting in partial or complete occlusion of the arterial lumen. "To interrogate whether smooth muscle OGT plays a direct role in development of atherosclerosis, we next generated smOGTKO mice on an ApoE-/- atherosclerotic background." (PMID 37175604, 2023). "Therapeutic strategies targeting glycosylation pathways, particularly O-GlcNAc transferase (OGT), and O-GlcNAcase (OGA), hold promise for addressing myocardial ischemia-reperfusion injury, diabetic cardiomyopathy, and atherosclerosis." (PMID 40458788, 2025).
Autoimmunity (2 papers, 2019 to 2022). The occurrence of an immune reaction against the organism's own cells or tissues. "Here the authors show that O-GlcNAcylation of Foxp3 and Stat5, mediated by O-GlcNAc transferase (OGT), is essential for Treg-mediate immune balance, with Treg-specific deficiency of OGT leading to severe autoimmunity." (PMID 30664665, 2019).
brain infarct (2 papers, 2017 to 2025). "We found that when the elevation of O-GlcNAcylation was partially diminished, the MCAO-induced brain infarct size was larger and the motor deficits were more severe in the neuronal OGT KO mice than in control mice." (PMID 28878265, 2017).
chronic kidney disease (2 papers, 2021 to 2024). Impairment of the renal function secondary to chronic kidney damage persisting for three or more months. "Chronic kidney disease (CKD) was induced by an adenine diet in mice, followed by injection of adenovirus vector carrying short hairpin RNA targeting OGT, followed by behavioral tests and collection of the cerebral cortex for primary neurons." (PMID 34462420, 2021).
Cirrhosis (2 papers, 2022 to 2024). A chronic disorder of the liver in which liver tissue becomes scarred and is partially replaced by regenerative nodules and fibrotic tissue resulting in loss of liver function. "For example, complete knockout of OGT (loss of O-GlcNAc) in the liver resulted in fibrosis/cirrhosis, while increased O-GlcNAc was shown in a mouse model of renal fibrosis." (PMID 38665916, 2024).
colorectal tumor (2 papers, 2024). "OGT protein was also upregulated in the azoxymethane (AOM)/dextran sodium sulfate (DSS) colorectal tumor model." (PMID 38168435, 2024).
COVID-19 (2 papers, 2020 to 2021). A disease caused by infection with severe acute respiratory syndrome coronavirus 2. "Then, we further investigated the function of OGT to explore the potential mechanism of PANO1 in the risk of COVID-19." (PMID 34290742, 2021). "As genes related to neurological disease and risk genes for COVID-19, OGT, and PANO1 must be considered further." (PMID 34290742, 2021).
depression (2 papers, 2023). "Here, we show that Ogt mRNA was increased in depression patients and that astroglial OGT expression was specifically upregulated in the medial prefrontal cortex (mPFC) of susceptible mice after chronic social-defeat stress." (PMID 36757814, 2023). "Our findings indicate that OGT in astrocytes acts as a stress sensor and modulates depression-related behaviors." (PMID 36757814, 2023). "In the present study, we found that astrocytic OGT in the mPFC was increased in mice with depression." (PMID 36757814, 2023). "OGT in astrocytes was upregulated in a depression model and was sufficient to bidirectionally regulate susceptibility to stress in the mPFC, but not in neurons." (PMID 36757814, 2023). "Stress is an important precursor for depression, and OGT acts as a nutrient and stress sensor." (PMID 36757814, 2023). "In this issue of the JCI, Fan and coauthors report that elevated posttranslational modification with the glucose metabolite N-acetylglucosamine (GlcNAc) by O-GlcNAc transferase (OGT) contributed to stress-induced establishment of depression-like behaviors in mice." (PMID 37009895, 2023).
glioma (2 papers, 2023 to 2025). A benign or malignant brain and spinal cord tumor that arises from glial cells (astrocytes, oligodendrocytes, ependymal cells). "This suggests that OGT and possibly OGA through O-GlcNAcylation may mediate glioma progression through transcriptional regulation of these genes." (PMID 37689115, 2023).
Hypertension (2 papers, 2022 to 2023). The presence of chronic increased pressure in the systemic arterial system. "Furthermore, it seems clear that O-GlcNAcylation, as well as OGT, play an important role on T and B cell activation, immune cells that are enrolled in the hypertensive disease." (PMID 35371030, 2022).
intrahepatic cholangiocarcinoma (2 papers, 2024 to 2025). A carcinoma that arises from the intrahepatic bile duct epithelium in any site of the intrahepatic biliary tree. "Our research has also found that USP8 stabilizes OGT through deubiquitination, thereby promoting the progression of intrahepatic cholangiocarcinoma (ICC)." (PMID 40607251, 2025).
laryngeal carcinoma (2 papers, 2015 to 2016). Carcinoma that arises from the laryngeal epithelium. "It should be emphasized that in our study, hyper-O-GlcNAcylation levels in laryngeal cancer tissue compared with normal mucosa was associated with an increased level of both OGT and OGA proteins." (PMID 25315705, 2015). "In human laryngeal cancer, the increased level of OGT mRNA was also related to a larger tumor size, nodal metastases, and a higher grade as well as the incidence of disease recurrence." (PMID 27542217, 2016). "The mRNA OGT level in laryngeal cancer tissue was significantly related to local tumor extension (pT) and nodal metastases (pN) (p < 0.0001 and p < 0.0001, respectively) as well as degree of histological differentiation (grade) (p = 0.003)." (PMID 25315705, 2015). "As a result, a positive expression of OGT protein was noticed in half the samples (5/10) of poorly differentiated laryngeal cancer (grade 3), 58.3 % (7/12) of moderately differentiated tumors (grade 2) and 20 % (2/10) of well-differentiated tumors (grade 1)." (PMID 25315705, 2015). "Of the laryngeal cancer samples, 5 of the 22 pN0 tumors (22.7 %) and 9 of the 10 pN1–3 tumors (90 %) demonstrated positive expression of OGT." (PMID 25315705, 2015). "Of 32 laryngeal cancer samples, OGT protein-positive expression was noticed in 47.1 % (8/17) and 40 % (6/15) tumors classified according to pTNM as pT3–pT4 and pT1–pT2, respectively." (PMID 25315705, 2015). "A significant difference in OGT and OGA protein levels was noted in laryngeal cancer tissue compared with adjacent normal laryngeal mucosa (p = 0.0004 and p = 0.007, respectively)." (PMID 25315705, 2015). "In this context, further studies of the precise roles of OGT and OGA and understanding the regulatory mechanisms occurring in laryngeal cancer will be needed." (PMID 25315705, 2015). "Positive expressions of OGT and MGEA5 transcripts was observed in 80 of 106 (75.5 %) and 73 of 106 (68.9 %) laryngeal cancer samples, as well as in 42 of 73 (57.5 %) and 29 of 73 (39.7 %) normal laryngeal tissue samples, respectively." (PMID 25315705, 2015). "The results of the Spearman rank correlation showed that OGT and MGEA5 transcript levels in laryngeal cancer were positively correlated (r = 0.39, p = 0.001)." (PMID 25315705, 2015). "However, it should be emphasized that more advanced tumors (pT3–pT4, N1–3) were more commonly found to be positive in a quantitative densitometric analysis, and to have higher mean OGT and OGA protein levels, than less advanced laryngeal cancers." (PMID 25315705, 2015). "The next stage also investigated whether OGT and OGA proteins can potentially determine the pTNM classification features of laryngeal cancer, since the tumor stage is currently the only accepted prognostic marker." (PMID 25315705, 2015).
medulloblastoma (2 papers, 2022 to 2023). A malignant, invasive embryonal neoplasm arising from the cerebellum. "In the cerebellum, OGT in granule precursor cells mediates the cerebellar development and the progression of the Shh subgroup of medulloblastoma, and OGT is highly expressed in the PCs." (PMID 37107182, 2023).
myocardial infarction (2 papers, 2020 to 2024). Gross necrosis of the myocardium, as a result of interruption of the blood supply to the area, as in coronary thrombosis. "However, after the administration of OGT inhibitor, the myocardial infarct size was significantly increased in the SPC+OSMI-1 group compared to the SPC group (44.35±3.34% vs. 30.96±1.81%, P<0.05)." (PMID 33231560, 2020).
Myoepithelioma (2 papers, 2021 to 2022). "Recently, two cases of myoepithelioma-like tumors of the hands and one case of the foot were described with previously never reported OGT-FOXO gene fusions." (PMID 33506328, 2021).
non-small cell lung carcinoma (2 papers, 2024 to 2025). A group of at least three distinct histological types of lung cancer, including non-small cell squamous cell carcinoma, adenocarcinoma, and large cell carcinoma. "This inhibition of paraspeckle-like structure formation was confirmed by siRNA knockdown of OGT in HCT116 cells, human breast adenocarcinoma MCF7 cells, and human non-small cell lung cancer A549 cells." (PMID 40360465, 2025).
nutritional disorder (2 papers, 2025 to 2026). Any condition related to a disturbance between proper intake and utilization of nourishment. "Lastly, due to the tight relationship between O-GlcNAcylation and de novo lipogenesis, investigating OGT-FASN interaction in pathologies associated with nutritional disorders would be of great interest." (PMID 41550490, 2026).
osteoarthritis (2 papers, 2024 to 2025). A noninflammatory degenerative joint disease occurring chiefly in older persons, characterized by degeneration of the articular cartilage, hypertrophy of bone at the margins and changes in the synovial membrane. "A recent study has shown that OGT-induced NEK7 O-GlcNAcylation levels were increased in both osteoarthritis and its experimental models, and knockout of OGT could alleviate osteoarthritis progression in model mice." (PMID 41350524, 2025). "It is still uncertain whether the O-GlcNAcylation inhibitor ST045849 can inhibit OGT and affect the progression of osteoarthritis." (PMID 39742284, 2024).
periodontitis (2 papers, 2024 to 2025). An acute or chronic inflammatory process that affects the tissues that surround and support the teeth. "Conversely, in periodontitis and osteoarthritis, OGT-mediated O-GlcNAcylation of NLRP3 or GSDME enhances pyroptosis and exacerbates inflammation." (PMID 41280891, 2025). "For example, the application of OGA inhibitors during sepsis may help improve hypoperfusion, while OGT inhibitors could play an anti-inflammatory role in periodontitis." (PMID 39742284, 2024). "Applying OGT inhibitors to patients with periodontitis could be an effective treatment strategy." (PMID 39742284, 2024).